PABPC1P2 (poly(A) binding protein cytoplasmic 1 pseudogene 2)
Synonyms: PABP2; PABP4; formerly PABPCP4; PABPCP2
Gene: Processed pseudogene on chromosome 2 (146,587,506 to 146,589,310, forward strand). Ensembl gene ENSG00000198526.
Diseases named in the same sentence as PABPC1P2 in open-access papers:
PABPC1P2 is named in the same sentence as 1 disease in open-access papers, as found by Europe PMC text mining. Sharing a sentence is not in itself a finding about the gene and the disease. The quoted sentences say what the papers report.
schizophrenia (1 paper, 2019). A major psychotic disorder characterized by abnormalities in the perception or expression of reality. "PABPC1P2 was associated with schizophrenia and OBFC1 as a locus involved in human leukocyte telomere biology in previous GWASs37,38." (PMID 31316127, 2019).